EGFR (epidermal growth factor receptor)
Diseases named in the same sentence as EGFR in open-access papers (continued):
Sharing a sentence is not in itself a finding about the gene and the disease.
meningioma (continued). "In our study, we determined the expression of EGFR in meningiomas by immunohistochemical analysis of archival tissue, and EGFR expression was detected in 86% of all meningiomas tested." (PMID 20509969, 2010). "Results also revealed that EGF (100 ng/mL, 48 h), an agonist of EGFR signaling, could remarkably upregulate PD‐L1 protein expression in NF2‐associated meningioma cells, demonstrating that EGF can induce an increase in PDL1 expression." (PMID 38828669, 2024). "More than half of meningiomas exhibit overexpression of EGFR." (PMID 36672431, 2023). "EGFR vIII staining intensity/expression of meningioma samples (grade I and II), n (%)." (PMID 34582442, 2021). "Here, the study aims at assessing the role of EGFR vIII as a tumorigenic factor in meningiomas." (PMID 34582442, 2021). "Expression of FACS EGFR VIII positive cells (%) in meningioma grade I and II patients." (PMID 34582442, 2021). "When percentages of EGFR-positive cells after normalized subtraction were compared, a significant reduction was found in the mean value of Grade II (12.9%) as compared to the mean value of Grade I (28.2%) meningioma patients." (PMID 34582442, 2021). "Although the whole mechanism should be additionally studied to give a thorough understanding of the activating cascade and all the partners involved in it, our studies set the basis for re-evaluating EGFR inhibition in meningioma as a possible therapeutic option." (PMID 32642677, 2020). "Over-expression of epidermal growth factor receptor (EGFR) is found in over 60% of meningiomas." (PMID 32974188, 2020). "Alternatively, amphiregulin and HB-EGF may act as activators of EGFR that is overexpressed in meningiomas, supporting tumor growth and malignancy." (PMID 31649887, 2019). "In the majority of meningiomas, both EGFR and its ligand EGF are overexpressed." (PMID 31970090, 2019). "Although the role of EGFR in meningioma treatment remains uncertain, our results suggest verteporfin may offer a new therapeutic action via this pathway." (PMID 29558515, 2018). "Notably, EGFR inhibition has yielded disappointing response rates in meningioma despite high EGFR expression." (PMID 30202034, 2018). "Thus, the prognostic value of EGFR in human meningiomas appears uncertain and needs to be further clarified." (PMID 28367377, 2017). "EGFR signaling which has earlier been reported in context to meningiomas were also found to be perturbed along with several other growth factor mediated signaling namely FGF signaling pathway, NGF mediated signaling, PDGF signaling and signaling by insulin receptors." (PMID 28938569, 2017). "EGFR expression also varied with regard to meningioma subtypes, suggesting that EGFR may play different roles in tumorigenesis of these variants." (PMID 28367377, 2017). "EGFR is overexpressed and in an activated state in human meningiomas." (PMID 28367377, 2017). "EGFR family members (EGFR, ErbB2–4) have been evaluated concomitantly in glioma and meningioma." (PMID 27091344, 2016). "Epidermal growth factor receptor (EGFR) can be activated through an autocrine loop by expression of EGFR ligands, EGF, and TGF-alpha (transforming growth factor alpha; increased expression linked to aggressive meningioma proliferation)." (PMID 25485306, 2014). "In the light of all the presented facts it appears that PI3K and its co-regulators may be more reasonable molecular targets in meningiomas than EGFR." (PMID 24932282, 2014). "Although these mutations appear to be rare, this result, along with previously reported findings, indicates that the PI3K/protein kinase B pathway may serve as a more reasonable molecular target for meningioma than EGFR." (PMID 24932282, 2014). "Depending on studies, the percentage of meningiomas that overexpress EGFR varied from 40 to 100%." (PMID 22623992, 2012). "This suggests that the oncogenetic mechanisms involving the EGFR gene pathway in meningiomas could be different from other tumor types." (PMID 22623992, 2012).
meningioma (continued). "In the present study, we investigated the EGFR expression pattern of meningiomas." (PMID 22623992, 2012). "In our series, the presence of EGFR mRNAs suggests that a particular regulatory mechanism of EGFR signaling could exist in meningiomas." (PMID 22623992, 2012). "In this study we described the EGFR-based profiling of meningiomas." (PMID 22623992, 2012). "In meningiomas, the role of EGFR signaling pathway in tumor genesis and the usefulness of EGFR investigation in regard to prognosis and/or theragnosis assessment remain unclear and discrepancies exist." (PMID 22623992, 2012). "In meningiomas, EGFR expression investigations mainly focused on EGFR isoform a." (PMID 22623992, 2012). "EGFR expression was detected in 86% of all meningioma samples tested." (PMID 20509969, 2010). "This study was designed to determine whether meningiomas express EGFR, and if so, to establish a correlation between the histopathologic grade of these tumors and the degree of EGFR expression." (PMID 20509969, 2010). "This study explores whether meningioma expresses epidermal growth factor receptor (EGFR) and determines if there is a correlation between the WHO grade of this tumor and the degree of EGFR expression." (PMID 20509969, 2010). "Therefore, we conclude that EGFR expression is inversely correlated with tumor grade in meningiomas." (PMID 20509969, 2010). "Percentage of EGFR staining (immunoreactivity) of meningioma samples, n (%)." (PMID 20509969, 2010). "The primary objectives of the study are to determine if EGFR is expressed in meningioma and whether there is a correlation between the WHO tumor grade of this tumor and the degree of EGFR expression." (PMID 20509969, 2010). "The discrepancies in the literature regarding the expression levels of EGFR in meningiomas may be accounted for by the different techniques used in each of these studies." (PMID 20509969, 2010). "In addition to PDGFR, overexpression of EGFR has been identified in more than 60% of meningiomas." (PMID 40113789, 2025). "Additionally, we measured the expression level of EGFR in NF2‐assoicated meningioma cells." (PMID 38828669, 2024). "Therefore, it is reasonable to evaluate whether these agents might be effective against meningiomas despite the failure of first-generation EGFR inhibitors." (PMID 36672431, 2023). "Furthermore, the expression of EGFR was higher in CD47 high expression group, which suggesting CD47 may affect the progression of meningioma by affecting EGFR pathway." (PMID 37171006, 2023). "Different growth factor receptors and kinases may promote the meningioma growth, including epidermal growth factor receptor (EGFR), platelet-derived growth factor receptor β (PDGFRβ), vascular endothelial growth factor receptor (VEGFR), and insulin-like growth factor receptor (IGFR)." (PMID 35565385, 2022). "Hence, Opinions regarding the role that EGFR vIII in tumorigenesis and tumor progression are clearly conflicting and, therefore, it is crucial not only to find out its mechanism of action, but also to definitely identify its role in meningioma." (PMID 34582442, 2021). "However, the role of EGFR vIII in meningioma is still in question." (PMID 34582442, 2021). "The lack of mutations in the EGFR TK domain and the downstream proteins that have been observed may indicate a low importance of this pathway in the growth of meningiomas, despite a previously suggested hypothesis." (PMID 24932282, 2014). "In addition, the occurrence of soluble EGFR isoforms, as detected in meningiomas, presumably unresponsive to tyrosine kinase inhibitor therapy, might also dampen the therapeutic response." (PMID 24428911, 2014). "The results show that known predictive markers have no value in meningiomas, and the lack of EGFR and downstream protein mutations may partially explain the results of the clinical trials with the anti-EGFR inhibitors, erlotinib and gefitinib." (PMID 24932282, 2014).
meningioma (continued). "The purpose of the mutation screening in the present study was to assess whether it is possible to use the molecular background to identify meningioma patients who may have a potentially improved response to anti-EGFR treatment, as is possible in the case of other tumors." (PMID 24932282, 2014). "In light of this, the expression of EGFR, p-ERK and β-catenin in meningioma tissues from WHO grade I, II and III was examined by immunohistochemistry." (PMID 37171006, 2023). "Along with that, the expression of p-ERK and EGFR was also remarkablely down-regulated in si-CD47 group cells, indicating the MAPK and EGFR signaling pathways were regulated by CD47 in malignant meningioma cells." (PMID 37171006, 2023). "Another active signaling pathway in meningioma is the RAS/RAF/MEK/MAPK pathway, which transduces the VEGFR, EGFR and PDGFR’s pro-mitotic signals." (PMID 36672431, 2023). "The results showed that p-ERK, EGFR and β-catenin were expressed in all grades of meningioma with the highest expression levels in WHO grade III meningioma." (PMID 37171006, 2023). "An overview of early investigations and different clinical reports showed that altered expression of EGFR, PDGFR, and VEGFR in meningioma, which is one of the most important aspects of carcinogenesis, has been widely studied." (PMID 37887327, 2023). "Our study identified two different ligands of EGFR, amphiregulin (AREG) and heparin-binding EGF (HB-EGF) that are elevated in the sera of Grade I meningioma patients." (PMID 31649887, 2019). "In the present study we have demonstrated that EGFR and its ligands EGF and TGFα are widely expressed in human meningiomas and that the receptor appears to be in an activated state." (PMID 28367377, 2017). "It has been shown that receptor tyrosine kinases such as epidermal growth factor receptor (EGFR) and platelet-derived growth factor receptor (PDGFR) are widely expressed in meningioma tumour cells." (PMID 27429002, 2016). "Similarly, the epidermal growth factor receptor (EGFR), and both their EGF and transforming growth factor-alpha (TGFα) ligands, as well as some members of the insulin-like growth factor (IGF) system (e.g. IGF2), have all been associated with meningioma cell proliferation and tumor progression." (PMID 25965831, 2015). "Despite this, a study involving 25 patients with recurrent meningioma treated with a combination of EGFR inhibitors gefitinib and erlotinib found no significant clinical response." (PMID 40113789, 2025). "PDGFR, EGFR, and VEGFR may have a dual activity on the RAS–RAF–MEK–MAPK or FAK–PI3K–AKT pathway, resulting in growth-favoring signals in meningiomas." (PMID 35565385, 2022). "Quantitative real-time RT-PCR revealed pronounced EGFR vIII mRNA expression that was absent in the majority of meningioma tissue specimens analyzed." (PMID 34582442, 2021). "Hence, we showed that EGFR is responsible for STAT1 overexpression and constitutive activation in meningioma, which consequently increases the proliferation of the tumor cells." (PMID 32642677, 2020). "This is also consistent with a previous study reporting that EGFR expression occurs less frequently in malignant meningiomas than in GI patients, and EGFR-positive patients have an improved survival prognosis compared with EGFR-negative patients." (PMID 24932282, 2014). "Previous meningioma studies have shown that EGFR does not undergo gene amplification, but to the best of our knowledge the point mutations in the TK domain of the receptor, which is encoded by exons 18–21, have not been analyzed." (PMID 24932282, 2014). "This is in line with previous studies that report no incidence of EGFR gene amplification in meningiomas, as these molecular aberrations have a similar effect on signal transduction." (PMID 24932282, 2014). "This in turn indicates that the EGFR pathway is not a promising target for the treatment of meningiomas." (PMID 24932282, 2014).
meningioma (continued). "The lack of consensus in meningiomas regarding EGFR can be attributed to primary antibodies used in immunohistochemistry (IHC) or to primer locations when RT-PCR approaches were used." (PMID 22623992, 2012). "In conclusion, we observed that, in addition to the entire EGFR isoform a (HER1), meningiomas expressed EGFR receptors lacking the ICD that was sustained by the strong expression of the EGFR transcripts encoding sEGFR isoforms." (PMID 22623992, 2012). "Our IHC results suggest that meningiomas express other EGFR isoforms than the whole receptor, but do not indicate which ones." (PMID 22623992, 2012). "While the majority of studies previously reported a specific EGFR immunoreactivity in the vascular endothelial cells of meningiomas, there were others that demonstrated no such correlation." (PMID 20509969, 2010). "Also, the combination more effectively blocked ligand-mediated phosphorylation of EGFR, ErbB3, and IGF-1R and elicited major changes in the expression of genes, including the upstream regulators of several signaling networks important for meningioma growth." (PMID 41417846, 2026). "Although the treatment was well tolerated, the lack of efficacy suggests that EGFR alone may not be a sufficient target for meningioma therapy." (PMID 40113789, 2025). "The detection of EGFR vIII was not reflected in meningiomas specimens." (PMID 34582442, 2021). "The IHC findings suggest that EGFR vIII could be a part of tumorgenicity of meningiomas but other analytical techniques does not support the claim." (PMID 34582442, 2021). "EGFR activates several downstream pathways, primarily those of mitogen-activated protein kinase (MAPK), phosphatidylinositol-4,5-bisphosphate 3-kinase/protein kinase B (PI3K/AKT) and phospholipase C, which have been found to play a role in meningioma pathogenesis." (PMID 24932282, 2014). "The results of studies on EGFR expression in meningiomas are not entirely consistent." (PMID 24932282, 2014). "Moreover, it can also be said that EGFR vIII does not have any significant role in meningioma." (PMID 34582442, 2021). "The increased levels of EGFR may be a result of enhanced transcription, translation or decreased receptor turnover, but is not likely due to gene amplification, as this is not described in meningiomas." (PMID 28367377, 2017). "Thus, activation of the EGFR pathway could represent a first step in meningiomas oncogenesis, whereas transformation in more aggressive tumors and/or the development of primary grade III meningiomas could result from additional oncogenic mechanisms." (PMID 22623992, 2012). "The authors speculate that activation of EGFR is not a result of any mutations of the EGFR, but it is secondary to autocrine/paracrine stimulation by their endogenous ligands, EGF and TGF alpha, which are also expressed in meningiomas and may contribute to meningothelial cell proliferation." (PMID 20509969, 2010).
gastrointestinal stromal tumor (39 papers, 2004 to 2025). "Examples of this principle include imatinib treated gastrointestinal stromal tumors and EGFR-TKI treatment for EGFR mutated advanced NSCLC." (PMID 27137772, 2016). "Synovial sarcomas, myxoid/round-cell liposarcomas, and gastrointestinal stromal tumors clustered tightly within the former cluster and discriminatory signatures for these were characterized by developmental genes from the EGFR, FGFR, Wnt, Notch, Hedgehog, RAR and KIT signaling pathways." (PMID 17359542, 2007). "Unlike the paradigm of imatinib mesylate in gastrointestinal stromal tumours where patients exhibit a relatively homogeneous phenotype, there seems to be no easily identifiable human cancer phenotype with a strong EGFR dependence." (PMID 15150574, 2004). "Selective tyrosine kinase inhibitors have shown promise in treating cancers driven by activated tyrosine kinases such as EGF receptor (EGFR) in non-small cell lung cancer (NSCLC), Bcr-Abl in chronic myelogenous leukemia (CML), and c-Kit in gastrointestinal stromal tumors (GIST)." (PMID 30885237, 2019). "FDA: Food and Drug Administration; ULN: Upper limit of normal; AST: Aspartate transaminase; ALT: Alanine transaminase; VEGFR: Vascular endothelin growth factor receptor; GIST: Gastrointestinal stromal tumor; PDGFR: Platelet-derived growth factor receptor; EGFR: Epidermal growth factor receptor." (PMID 30116677, 2018).
gastric tumors (38 papers, 2008 to 2026). "However, recent reports suggested the clinical feasibility of EGFR-mediated therapy, especially for patients with EGFR amplification in gastric tumors, and revealed potential mechanisms underlying EGFR therapeutic resistance." (PMID 32070411, 2020). "EGFR is overexpressed in a significant fraction (27%–64%) of gastric tumors, where its oncogenic role has been well-characterized." (PMID 37175811, 2023). "Using mass spectrometry-based genotyping we analysed 105 hotspot, non-synonymous somatic mutations in PIK3CA and ERBB-family (EGFR, ERBB2, ERBB3 and ERBB4) genes in gastric tumour samples from 69 patients." (PMID 33933113, 2021). "We identified lineage-specific drug sensitivities based on histopathological and molecular subclassification, including substantial sensitivities toward VEGFR and EGFR inhibition therapies in diffuse- and signet ring-type gastric tumors, respectively." (PMID 32070411, 2020). "In Gan mouse gastric tumors, PGE2 signaling through EP4 receptor activates signaling through epidermal growth factor receptor (EGFR), which causes promotion of gastric tumorigenesis." (PMID 30700829, 2019). "CD24 and EGFR expression patterns in human gastric tumor samples were also investigated by immunohistochemistry staining." (PMID 26830684, 2016). "The aim of the present study was to evaluate EGFR and HER-2 immunohistochemical expression and KRAS mutational status in a series of canine gastric tumours." (PMID 24454858, 2014). "The EGFR protein was expressed in 52.2% (36/69) of gastric tumors, and EGFR gene amplification occurred in 29.0% (20/69) of tumors." (PMID 21689422, 2011). "Both gastric tumor cell lines were screened for EGFR and only one of the two patient tumor cell lines (patient 1) expressed EGFR." (PMID 20937115, 2010). "Eleven percent of the cases showed EGFR expression levels corresponding to 3+, 31% showed EGFR levels of 2+, and 5% showed EGFR levels of +; the remaining 53% of cases showed level 0 staining (n = 100 gastric tumor samples)." (PMID 19061514, 2008). "The combined overexpression of MET, HER2 and EGFR was observed in 3% of gastric tumors." (PMID 31557260, 2019). "In gastric tumours, data concerning structural alterations of EGFR remains controversial." (PMID 18199332, 2008). "Furthermore, the prolonged exposure of gastric neoplasms to trastuzumab-based regimens favors the temporal loss of HER2 overexpression, and the concomitant upregulation of bypass signaling circuits sustaining tumor cell proliferation and survival (e.g., EGFR and c-Met-mediated signaling)." (PMID 38539559, 2024). "Other molecular mechanisms leading to gastric tumors include the activation of RTKs, especially epidermal growth factor receptor (EGFR) (also known as HER1/ErbB1) by Helicobacter pylori (H. pylori)." (PMID 38186572, 2023). "Gastric tumor histology confirmed the expression of HER2 and EGFR." (PMID 25862542, 2016). "However, Both ERBB2 and EGFR gene amplification of gastric tumors were 3 cases (4.3%), but abnormalities both ERBB2 and EGFR gene copy number were present in 36.2% of samples." (PMID 21689422, 2011). "Since most of the ChemBridge compounds have good drug-like properties, we hypothesize that with further evaluations in higher models, C3 could be developed as a selective dual inhibitor of EGFR/HER2 kinase as a treatment regimen for solid tumors, especially gastric tumors." (PMID 38186572, 2023).